CD44 (CD44 molecule (IN blood group))
Diseases named in the same sentence as CD44 in open-access papers (continued):
Sharing a sentence is not in itself a finding about the gene and the disease.
pancreatic cancer (continued). "They compared the tumorigenicity of different sets of primary tumor cells and identified that c-Met high cancer cell population had the highest tumorigenic potential, compared with pancreatic cancer cells expressing CD44, CD24, ESA and CD133." (PMID 28245823, 2017). "ZEB1 enforces CD44 isoforms (CD44s) splicing by repression of epithelial splicing regulator ESRP1 in pancreatic cancer." (PMID 28245823, 2017). "Pancreatic tumours with impaired expression of Six1 showed significantly delayed growth and displayed loss of the CD24+/CD44+ phenotype." (PMID 28388884, 2017). "Pancreatic cancer stem cells had been initially identified in 2007 by Li and coworkers who investigated the expression of CD44, CD24 and epithelial-specific antigen (ESA) in pancreatic tumors." (PMID 29156578, 2017). "Li and colleagues firstly identified that CD44+/CD24+/ESA+ pancreatic cancer cells showed the stem cell properties, including self-renewal, multi-differentiation and tumorigenicity." (PMID 26840020, 2016). "Real-time PCR and flow cytometry confirmed that FH535 downregulated CD24 and CD44, pancreatic cancer stem cell (CSC) markers, suggesting FH535 impairs pancreatic CSC stemness." (PMID 27323403, 2016). "CD24+/CD44+ pancreatic cancer cells have a significantly higher possibility for forming colonies in vitro and are more resistant to irradiation." (PMID 27323403, 2016). "In the pancreatic cancer cells L3.6pl contained 59.1% CD24+/CD44+ cells of which 94.9% were EpCAM+/CD166+, yielding a 56.1% CSC subset." (PMID 27512958, 2016). "Pancreatic cancer cells expressing the cell surface marker CD44+ CD24+ ESA+ phenotype had a 100-fold increased tumorigenic potential compared to non-tumorigenic cancer cells." (PMID 27649156, 2016). "CSC populations at basal level were detected in PANC-1 cells using multi-fluorescence labeled flow cytometry to identify CD24+CD44+EpCAM+ cells, as these cellular surface markers were indicative for pancreatic cancer stem cells." (PMID 27764163, 2016). "Presently, we discovered that FH535 decreased the population of CD24+/CD44+ pancreatic cancer cells, the presumed pancreatic CSCs." (PMID 27323403, 2016). "Markers for prospectively identifying pancreatic cancer stem cells are CD44+CD24+EpCAM+, CD133+, and ALDH+." (PMID 26673007, 2016). "Our previous studies though showed that CD24+CD44+ cells isolated from a human pancreatic carcinoma cell line (PANC-1) had 4-fold increased invasion ability compared to CD24-CD44+ cells." (PMID 27332878, 2016). "This pathway has been reported to activate CD44+ breast CSCs, whereas it also diminish the population of tumor initiating cells of gastric and pancreatic cancer." (PMID 26110809, 2015). "A recent study using mouse pancreatic tumor cells shows that CD44 is expressed on a specific population of pancreatic cancer cells." (PMID 25954275, 2015). "This provide preliminary direct evidence for the possibility of CD44 regulating the metastasis of pancreatic cancer." (PMID 26666511, 2015). "By IHC analysis, (64.6 %) and 14 (29.2 %) paraffin-embedded archival pancreatic tumor tissues showed a positive staining for CD44 and p-AKT." (PMID 26666511, 2015). "Our previous study also showed that stable knockdown of CD44 expression in pancreatic cancer cells can inhibit proliferation and migration in pancreatic cancer cells." (PMID 26666511, 2015). "Taken together, our results showed that IMP3 expression promotes matrix adhesion, motility and invasion of pancreatic cancer cells by enhancing CD44 and KIF11 expression." (PMID 25886367, 2015). "CD44+/c-Met+ cells have been demonstrated to be tumorigenic with stemness characteristics in pancreatic cancer, which suggests a dual role of c-Met and CD44 as regulators of tumor initiation." (PMID 25886575, 2015). "To assess the correlation of OPN with LC3/ALDH1 and CD44/CD133 coexpression in pancreatic tumor specimens, we performed triple immunofluorescence staining in TMAs." (PMID 26458814, 2015).
pancreatic cancer (continued). "Some cell surface markers have been reported as CSC markers in pancreatic cancers, such as CD44, CD133, ALDH1, and ABCG2, and high expression of these markers is usually considered an indicator of poor prognosis." (PMID 26666511, 2015). "There was a significant difference between the CD44 expression and the pancreatic cancer’ T staging, tumor node metastasis (TNM) staging, lymph node metastasis (P < 0.05)." (PMID 26666511, 2015). "In pancreatic cancer, where CD44 expression correlates with poor prognosis, intravenous delivery of an anti-CD44 monoclonal antibody H4C4 has been shown to completely inhibit tumor growth and metastasis in two different pancreatic xenograft models." (PMID 25954275, 2015). "Several cell-surface markers, including CXCR4, ALDH, CD24 and CD44 have been used to identify of cancer stem-like cells in pancreatic cancer." (PMID 25811929, 2015). "Researchers usually identified CSCs from pancreatic cancer based on the expression of the cell surface antigens like CD44, CD24, epithelial-specific antigen (ESA), and CD133." (PMID 24489910, 2014). "Pancreatic cancer cells treated with GSI showed a significant reduction in CSCs with the ESA+/CD44+/CD24+ marker profile compared to untreated cells (2.76±0.16% control vs. 1.43±0.15% with GSI p = 0.013)." (PMID 24647545, 2014). "Pancreatic cancer stem cells (CSC) were first isolated from human pancreatic cancers using the marker profile ESA+/CD44+/CD24+." (PMID 24647545, 2014). "Pancreatic cancer cells with EMT phenotype displayed stem-like cell features characterized by the expression of cell surface markers CD24, CD44 and epithelial-specific antigen (ESA), which was associated with decreased expression of miR-200a." (PMID 24521357, 2014). "Consistent with our observations, a highly tumorigenic subpopulation of cells with CD44+/CD24+/ESA + phenotype was identified as cancer stem cells in pancreatic cancer." (PMID 24612587, 2014). "KMC14 cells expressed mRNA of Notch-1, Notch-2, Jagged-1, c-Met, CXCR-4, CD24 and CD44, except Jagged-2, that were reported as pancreatic cancer markers." (PMID 24278411, 2013). "Because CD133+ and CD24+CD44+ESA+ cells have been documented to be pancreatic cancer stem cells, we determined the effect of low concentrations of metformin on these subpopulations, demonstrating a decreased proportion of CD133+ cells." (PMID 23667692, 2013). "This phenomenon was also observed in the study conducted by Huang and coworkers, where CD44+/CD24+ pancreatic cancer cells showed an exacerbated tumorigenic potential." (PMID 23419168, 2013). "Pancreatic cancer stem cells are commonly defined by expression of CD44, CD24, and ESA on the cell membrane surface." (PMID 24039920, 2013). "In a genetically engineered mouse model disseminating pancreatic cancer cells are enriched for CD44+CD24+ CSC compared to the primary PanIN lesion or tumor, and have increased proliferation rates and spheroid formation capacity in vitro." (PMID 24213498, 2012). "Single investigated CpG of p16 (OR 10.4, 95%CI 2.0-54.7), BCL2 (OR 33.8, 95%CI 3.6-314.3), CD44 (OR 10.3, 95%CI 2.0-52.3) and TNFRSF10C (OR 11.8, 95%CI 2.2-64.1) were associated with pancreatic cancer." (PMID 22629410, 2012). "SHH expression was ~46 times higher in CD44+CD24+ESA+ xenografted pancreatic tumor cells than in normal pancreatic epithelial cells, compared to a 4-fold increase of SHH expression in unsorted pancreatic cancer xenograft cells." (PMID 24213498, 2012). "Our current study clearly demonstrated that in vivo inhibition of pancreatic tumor initiating CD44+/EpCAM+ cells by GSI resulted in a down regulation of mesenchymal cell markers and up-regulation of epithelial cell markers and can suppress tumorigenesis." (PMID 23094026, 2012). "The pancreatic cancer cell line KP3 expressed 98% CD44 positive and 34% of EpCAM positive cells, but when the markers were sorted together only 19% of cells were positive for both of the markers." (PMID 23094026, 2012).
pancreatic cancer (continued). "We found however that spheres generated from CD44+/CD24+expressing pancreatic cancer cells also expressed CD133 as well as EpCAM." (PMID 22570653, 2012). "Based on the known roles of Notch in development and stem cell biology, we focused on effects on epithelial mesenchymal transition (EMT) and on pancreatic tumor initiating CD44+/EpCAM+ cells." (PMID 23094026, 2012). "In summary, the combination of quantitatively functionalized surfaces and statistical image analysis provides a basis for gaining spatio-temporal pattern formation in pancreatic cancer cells adhered via CD44-HA interactions." (PMID 22916191, 2012). "Another study identified c-MET-, CD44-, and α6β4-receptors as mediators of a tumor matrix triggered increase in migratory potential of pancreatic tumor cells." (PMID 24213498, 2012). "We investigated methylation levels at selected CpG sites in the CpG rich regions at the promoter regions of p16, RARbeta, TNFRSF10C, APC, ACIN1, DAPK1, 3OST2, BCL2 and CD44 in the blood of 30 pancreatic tumor patients and in the blood of 49 matching controls." (PMID 22629410, 2012). "In xenografts derived from primary pancreatic tumors the overlap between ALDHhigh and CD44+CD24+ cells was very limited." (PMID 24213498, 2012). "We analyzed the effect of the GSI IX on growth and epithelial plasticity of human pancreatic cancer cell lines, and on the tumorigenicity of pancreatic tumor initiating CD44+/EpCAM+ cells." (PMID 23094026, 2012). "For instance, CD44, a stem cell surface marker, is highly expressed in a tumorigenic subpopulation of pancreatic cancer cells." (PMID 22626610, 2012). "Given the ability of GSI to inhibit pancreatic tumor initiating CD44+/EpCAM+ cells in vitro, we further tested the in vivo role of GSI in a Xenograft nude mouse (NMRI-nu/nu) model." (PMID 23094026, 2012). "ARRs at physiologically achievable concentrations induce apoptosis of a number of pancreatic cancer cell lines as well as inhibit sphere formation by the CD44+/CD24+ stem-like cell population derived from the pancreatic cancer cell lines." (PMID 22570653, 2012). "Similar results were obtained when miR-34a was restored by exogenous miRNAs (pre-miR transfection or lentiviral expression) in another pancreatic cancer model resulting in an almost 90% reduction in tumor-initiating CD44+ stem cells." (PMID 23166734, 2012). "Specifically, the adhesion and motility of rat pancreatic cancer cells expressing different CD44 isoforms were studied on defined lateral densities of HA." (PMID 22916191, 2012). "CCE cells produced 3-fold more spheres than control cells and were more invasive, secreted more MMP-9, and overexpressed markers for pancreatic SCs/CSCs (i.e., CXCR4, OCT4, CD44) and S100P, a marker for pancreatic cancer." (PMID 22626610, 2012). "The rat pancreatic carcinoma model BSp73 provides a useful model for analyzing both the metastasis-promoting functions of CD44 as well as the interaction between CD44 and HA." (PMID 22916191, 2012). "The first report of isolation of pancreatic cancer cells with tumor-initiating properties resulted from selection of cells for CD44, CD24, and ESA (epithelial-specific antigen) cell surface expression." (PMID 21695188, 2011). "Here we characterized the malignant phenotypes of the pancreatic cancer stem CD44+/CD24+ cells, which were enriched under sphere forming conditions as analyzed by flow cytometry." (PMID 21673909, 2011). "In an in vitro setup, we have also demonstrated that stemness-like state can be achieved in the presence of Cyr61 through the regulation of multiple stemness traits including ABCG2, Notch-1, Oct-4 and CD-44 in pancreatic cancer cells." (PMID 21232118, 2011).
pancreatic cancer (continued). "Based on two independent reports, pancreatic cancer stem cells were identified as population of CD44+CD24+ESA+ or CD133+, however, these two populations showed little overlap with each other." (PMID 21826251, 2011). "The CD44+CD24+ESA+ pancreatic cancer cells are highly tumorigenic and possess the stem cell-like properties of self-renewal and the ability to produce differentiated progeny." (PMID 21304978, 2011). "Firstly, the cell surface markers of pancreatic cancer stem cells, CD44, CD24, and CD133, were evaluated." (PMID 21826251, 2011). "The elevation of GLI1 and GLI2 in holoclones suggests higher activity of Hedgehog signaling, which was consistent with the higher level of SHH expression in CD44+CD24+ESA+ cancer stem cells isolated from human primary pancreatic cancer specimens." (PMID 21826251, 2011). "ALDHhigh/CD44+/CD24+ cells comprised an average of 0.015% of all pancreatic cancer cells and ALDHlow/CD44+/CD24+ cells comprised 0.11% of all tumor cells." (PMID 21695188, 2011). "Previous reports demonstrated the enrichment of CSCs through the isolation of pancreatic cancer cells co-expressing the cell surface markers CD44 and CD24." (PMID 21695188, 2011). "In human pancreatic cancer samples CD44 expression was correlated with histological grade and patients with CD44 positive tumors showed poor prognosis." (PMID 24281171, 2010). "This subpopulation of pancreatic cancer cells with CD44+/CD24+/ESA+ phenotype (only 0.2 to 0.8% of pancreatic cancer cells) had a 100-fold increased tumorigenic potential compared with other cancer cells." (PMID 19602232, 2009). "CD44 promotes cancer stemness in pancreatic cancer through the SPP1-CD44 axis." (PMID 39919692, 2025). "This research could lay grounds for evaluating the efficacy of immunotherapy to target CD44-expressing CSCs in pancreatic cancers, potentially improving patient outcomes." (PMID 39148690, 2024). "Our data also indicates high Cd44 expression in neutrophils present in pancreatic tumors." (PMID 38987547, 2024). "Moreover, decreasing the expression of CD44 in pancreatic cancer is also a promising therapeutic strategy." (PMID 38783892, 2024). "Additionally, the expression levels of CD44, another cancer stem cell marker upregulated in pancreatic cancer cells undergoing EMT, were elevated in Panc-1 dsHSATII cells compared to in Panc-1 empty and HSATII Fw cells." (PMID 38346537, 2024). "This study aims to explore the efficacy of targeted nanoparticle (NP)-based small interfering RNA (siRNA) therapies in downregulating these genes to enhance treatment outcomes in pancreatic cancer, a tumor type characterized by high CD44 expression and hypoxia." (PMID 39458615, 2024). "HA‐based nanomicelles loaded with 3,4‐difluorobenzylidene curcumin could also kill CD44+ stem‐like pancreatic cancer cells." (PMID 38783892, 2024). "Hence, targeting CD44 drug delivery systems in cancer cells provide an avenue for pancreatic cancer treatment." (PMID 38783892, 2024). "Patients with CD44-expressed pancreatic cancers showed poor prognosis." (PMID 37108495, 2023). "Interestingly, the most tumorigenic subpopulation was found to be c-met/high/CD44+, with as few as 50 cells enough to develop pancreatic cancer in NOD/SCID mice, where the percentage of c-met and c-met/high cells ranged between 2–16%." (PMID 37371030, 2023). "Previous studies showed p-ezrin directly promotes cell mobility and migration in cancer cell lines through the activation of different signaling pathways, including Rac1, CD44 and Cdc42, while in pancreatic cancer ezrin activates FAK/Akt to promote proliferation." (PMID 36926194, 2023). "In addition, the p-Erk/p-p38 ratio was significantly enhanced and down-regulated CD44 expression by C4orf47 suppression, suggesting that C4orf47 is involved in pancreatic cancer dormancy under hypoxic conditions." (PMID 36741255, 2023).
pancreatic cancer (continued). "The selective lysis of pancreatic tumors by NK cells was strongly associated with higher expression of CD44, and no or low expression of CD54 and MHC-class I on CSCs/poorly differentiated histopathology." (PMID 37954598, 2023). "Paraffin samples of pancreatic cancers were stained with anti-CD44 antibody." (PMID 37108495, 2023). "In addition, the anti-CD147 drug metuximab sensitizes pancreatic cancer cells to chemoradiotherapy by reducing the CSC subpopulation via blockade of CD44/STAT3 signaling." (PMID 36902161, 2023). "Furthermore, metuximab sensitized pancreatic cancer cells to chemoradiotherapy by reducing the CSC subpopulation by blocking CD44/STAT3 signaling." (PMID 36012604, 2022). "We hypothesized that GABRP is required for CD44 isoforms to induce chemoresistance in pancreatic cancer." (PMID 35846884, 2022). "Moreover, CD44 was expressed higher in several solid tumors, such as pancreatic cancer, which was considered an important target for therapeutic." (PMID 36003146, 2022). "OPN is highly expressed in human pancreatic tumor cells and may bind to CD44 on tumor cells via autocrine and paracrine manners to promote pancreatic cancer stemness and progression." (PMID 36078039, 2022). "Unexpectedly, CD44 levels were higher in adjacent normal tissues than in pancreatic tumor tissues." (PMID 36292918, 2022). "The functions of various CD44 isoforms in pancreatic cancer are not fully understood." (PMID 35846884, 2022). "KLF4 as a tumor repressor negatively modulates CD44 and restrains metastasis of pancreatic cancer." (PMID 35027543, 2022). "We previously isolated pancreatic cancer cells based on CD44 differential expression levels." (PMID 35931675, 2022). "We built the first link between GABRP and gemcitabine in pancreatic cancer, and we report, for the first time, that GABRP might be downstream of the CD44 effector gene in gemcitabine-resistant pancreatic cancer cells." (PMID 35846884, 2022). "This study suggests that IGF1R-dependent CD44 isoform switching confers pancreatic cancer cells to undergo an adaptive change in response to gemcitabine and provides the basis for improved targeted therapy of pancreatic cancer." (PMID 35931675, 2022). "Targeting CD44-positive pancreatic cancer cells with HA-modified drugs." (PMID 34988078, 2021). "In human pancreatic cancer cells, CD44+/CD133+/EpCAM+ CSC-like cells exhibited lower levels of let-7 expression, and this suppressed let-7 expression promoted the expression of pluripotency transcription factor, such as NANOG, SOX2, SOX9, OCT4, KLF4 and c-myc, to maintain CSCs." (PMID 34572067, 2021). "Finally, we identified the surface protein CD44 as a promising therapeutic target for pancreatic cancer patients with high CFL1 expression." (PMID 33578795, 2021). "However, the efficacy of PAK1, TWIST1, or CD44 inhibition for pancreatic cancer treatment will have to be determined in further pre-clinical and clinical studies." (PMID 33578795, 2021). "Similarly, MEG3, an imprinted long non-coding RNA with tumor suppressor properties, decreased the number of CD44+/CD24+/ESA+ pancreatic cancer cells and the levels of Nanog and Oct4 expression." (PMID 34203589, 2021). "Our previous studies have established OSCSCs as oral and MP2 as pancreatic stem-like/poorly differentiated tumors and OSCCs and PL12 tumors as well-differentiated oral and pancreatic tumors, respectively using CD44, CD54, MHC-class I, and PD-L1 surface antigens." (PMID 33440654, 2021). "RPN2 is also highly expressed in the CD24+CD44+ cancer stem-like cells of pancreatic cancer." (PMID 33692975, 2021). "CD44 is a widely distributed cell surface marker, which is used to identify and enrich tumor stem cells in different types of cancer including breast, colon, liver, ovarian, pancreatic cancers." (PMID 32497020, 2020). "MUC4 regulates CD44 and c-Myc expression via β-catenin in pancreatic cancer cells." (PMID 33082357, 2020).